CRP (C-reactive protein)
Diseases named in the same sentence as CRP in open-access papers (continued):
Sharing a sentence is not in itself a finding about the gene and the disease.
cardiovascular disease (continued). "The prognostic value of high sensitivity C-reactive protein (hs-CRP) in prediction of cardiovascular disease has been suggested by many investigators." (PMID 25068056, 2014). "In any case, to overcome the alleged problem of insufficient CRP synthesis in mice, a transgenic mouse that overexpresses human CRP was generated, and this model is widely used to study the role of CRP in cardiovascular disease." (PMID 24872599, 2014). "Chronic stress has also been shown to induce a chronic and systemic state of mild inflammation (i.e., C-reactive protein and interleukin-6) a key mechanism in the development of cardiovascular disease." (PMID 25374338, 2014). "Hs-CRP is viewed as a predictor of cardiovascular disease, although the exact nature of its role remains controversial." (PMID 24669230, 2014). "CRP has been used as a general marker for inflammation and, more recently, for predicting cardiovascular diseases." (PMID 25587427, 2014). "High-sensitive C-reactive protein (hs-CRP) is a widely used marker for systemic inflammation and an independent predictor of cardiovascular disease." (PMID 24755038, 2014). "C-Reactive Protein (CRP) is a sensitive systemic marker of inflammation and was identified as a biomarker of cardiovascular diseases." (PMID 24588988, 2014). "In cardiovascular disease, elevated CRP and interleukin (IL)-6 levels correlate with adverse events." (PMID 23657512, 2013). "Epidemiological evidence for the role of inflammation in the etiology of coronary heart disease, myocardial infarction, and peripheral vascular disease has indicated a role for CRP as a biomarker for cardiovascular disease." (PMID 26317021, 2013). "Compared with the normoalbuminuria group, the microalbuminuria group had a greater age; higher waist circumference; history of cardiovascular disease; and higher systolic BP; diastolic BP; fasting blood glucose; triglycerides; and CRP levels." (PMID 23725496, 2013). "Among kidney disease patients serological biomarkers related to cardiovascular disease (fibrinogen, interleukin 6, C-reactive protein) were measured." (PMID 23294625, 2013). "In fact, the combination of Mg with a statin has been recently suggested as a potential and seemingly-promising avenue to reduce cholesterol, C-reactive protein, and cardiovascular disorders." (PMID 23418599, 2013). "In the last years, different markers of inflammation (such as CRP, IL-6, and TNF-alpha, among others) have been studied in prediction of coronary events; on this regard, CRP is the most important marker for cardiovascular disease." (PMID 23690772, 2013). "Blood levels of the acute phase proteins C-Reactive Protein (CRP) and Serum Amyloid A (SAA) are among the strongest known risk factors for cardiovascular diseases in prospective studies." (PMID 23894396, 2013). "C-reactive protein (CRP), serum amyloid P component (SAP) and pentraxin 3 (PTX3) are all pattern recognition proteins belonging to the pentraxin super family, where CRP is a well established plasma marker for cardiovascular disease." (PMID 24060373, 2013). "High sensitive (hs)-CRP has been recognized as an independent determinant of cardiovascular diseases and death in the elderly." (PMID 24244755, 2013). "Koenig et al31 in the population‐based Monitoring of Trends and Determinants in Cardiovascular Disease (MONICA) Study, demonstrated that CRP enhanced global coronary risk, as assessed by the Framingham Risk Score." (PMID 23525430, 2013). "CRP has been extensively studied in cardiovascular disease and much of this work has revolved around its effect on the endothelium." (PMID 24167754, 2013). "Many studies have focused on the CRP gene due to its perceived involvement in cardiovascular disease." (PMID 24167754, 2013). "CRP is an important biomarker for many aspects of health and disease, including cardiovascular disease, type 2 diabetes, and chronic renal disease and is a predictor of all-cause mortality." (PMID 26317021, 2013).
cardiovascular disease (continued). "Physical activity prevents cardiovascular disorders, which can be partly mediated through reducing inflammation, including serum CRP levels." (PMID 22524121, 2012). "C-reactive protein (CRP) is a sensitive marker of systemic inflammation and is an independent risk factor for cardiovascular disease." (PMID 23108518, 2012). "Cardiovascular diseases are accompanied by the elevation of several positive acute phase reactants such as CRP, serum amyloid A (SAA), fibrinogen, white blood cell count, secretory nonpancreatic phospholipase 2-II (sPLA2-II), ferritin, and ceruloplasmin." (PMID 24049653, 2012). "There is increasing evidence of a relationship between the serum level of CRP, a marker of chronic inflammation, and cardiovascular disease in these patients." (PMID 22583484, 2012). "High SHS was also associated with elevated C-reactive protein (CRP), which contributes to explaining the association between SHS and deaths due to cardiovascular disease (CVD)." (PMID 21556172, 2011). "South Asian Americans are generally more insulin resistant, have elevated CRP concentrations and more cardiovascular diseases despite sharing the similar feature of low BMI with East AA." (PMID 22164267, 2011). "CRP plays a significant role in atherogenesis in endothelial cells, next to vascular smooth muscle cells and macrophages, and several studies have revealed that CRP levels predict cardiovascular disease." (PMID 20634940, 2010). "It is now established that reduction in the plasma to adiponectin and increased PAI-1 and CRP levels play a role in the maintenance of an inflammatory state and in the development of cardiovascular disease." (PMID 20205861, 2010). "C-reactive protein is a well established marker of inflammation and has been used to predict future cardiovascular disease." (PMID 21062467, 2010). "Moreover, the results strongly suggest that further elevation of certain inflammatory markers, such as CRP, IL-6, and sVCAM-1, could be considered as markers of severity of cardiovascular disease and consequently higher risk of developing a cardiovascular event in dyslipidemic subjects." (PMID 19584917, 2009). "Serum levels of CRP are independent predictors for preclinical cardiovascular disease (CVD), cardiovascular events, and overall cardiovascular mortality in RA patients." (PMID 19606218, 2009). "C-reactive protein (CRP), a marker of sub-clinical inflammation, is a predictor of future cardiovascular diseases." (PMID 19822004, 2009). "Recent studies are now demonstrating that IL-6 and TNF-alpha are stronger predictors of cardiovascular disease than C-reactive protein." (PMID 17374166, 2007). "C-reactive protein (CRP) is an acute phase reactant, and has been reported as a predictor of cardiovascular diseases." (PMID 17641447, 2007). "In general, these studies indicate that D-dimer, similar to C-reactive protein (CRP), is a moderate but consistent and independent marker of risk of cardiovascular disease, both in population studies and in patients at risk." (PMID 15574198, 2004). "Individuals with elevated levels of both CRP and IL-6 face a heightened risk of mortality from cardiovascular diseases—this association remains independent of factors such as age, gender, body mass index (BMI), or medical history." (PMID 41590696, 2026). "The high-sensitivity C-reactive protein to albumin ratio (CAR) or C-reactive protein to albumin has emerged as a valuable prognostic indicator in various medical conditions including solid tumors, hematological malignancies, cardiovascular diseases and respiratory diseases." (PMID 40435309, 2025). "An increase in CRP directly affects the pathogenesis of cardiovascular disease in older adults." (PMID 40095921, 2025). "Furthermore, inflammation is a link between aging and cardiovascular disease, as aging presents with systemic low-grade chronic inflammation and elevated concentrations of mediators such as IL-6, TNFα, and C-reactive protein (CRP)." (PMID 40869066, 2025).
cardiovascular disease (continued). "Clinical evidence demonstrates that patients with advanced periodontitis exhibit higher circulating IL-6 and CRP levels correlated with reduced flow-mediated dilation, confirming the inflammatory–vascular link between periodontal infection and cardiovascular disease." (PMID 41294894, 2025). "At this point, it should be emphasized that increased CRP levels may also triggered by many disorders unrelated to cardiovascular disease, which interferes with clinical application." (PMID 39941424, 2025). "Therefore, it is of interest to evaluate the diagnostic accuracy of CRP and Troponin I, and to investigate thecomplementary role of IL-6, LDL-C, and HDL-C in predicting cardiovascular disease risk." (PMID 40978648, 2025). "Additionally, monitoring calcium and phosphorus metabolism, along with inflammatory markers (e.g., hs-CRP, SOST), can further reduce the risk of cardiovascular disease." (PMID 40314886, 2025). "Meanwhile, CRP has also been confirmed as a potent predictor of cardiovascular diseases." (PMID 41479545, 2025). "Elevated CRP levels in SLE patients are associated with cardiometabolic risk factors and clinical disease activity, highlighting the role of inflammation in the development of cardiovascular disease." (PMID 41289287, 2025). "Risk of cardiovascular disease upon co-exposure stratified by AIP and hs-CRP." (PMID 40842496, 2025). "Second, it is based on the well-established hs-CRP cut-offs, widely used in cardiovascular disease due to their standardization, along with the cut-off values for D-dimer from our prior publication, effectively representing the distribution of our patient population." (PMID 40563583, 2025). "C-reactive protein (CRP) is a sensitive marker for detecting inflammation, and the literature indicates that it serves as a valuable indicator of the inflammatory levels associated with cardiovascular disease." (PMID 40519908, 2025). "The combination of CRP with these and other emerging biomarkers could enhance the specificity and predictive power of inflammatory markers in cardiovascular disease." (PMID 40649166, 2025). "In individuals who smoke cigarettes, inflammatory markers, including CRP, are higher, and could be a link to cardiovascular disease." (PMID 40241094, 2025). "CRP participates in angiogenesis and atherothrombosis of cardiovascular disease." (PMID 40282303, 2025). "As a sensitive inflammation marker, CRP is crucial in predicting cardiovascular diseases." (PMID 41323647, 2025). "C-reactive protein to serum albumin ratio (CRA) is used as a marker of cardiovascular disease." (PMID 40667402, 2025). "Therefore, in clinical practice, CRP testing is widely used in various fields such as inflammatory diseases, cardiovascular diseases, and postoperative complications monitoring." (PMID 39996992, 2025). "However, as mentioned, CRP levels can also be influenced by factors unrelated to nutrition (e.g., cardiovascular diseases) and other inflammatory conditions (e.g., infections)." (PMID 41515189, 2025). "Moreover, CRP identifies and binds a variety of intrinsic ligands, which participate in the progression of cardiovascular disease." (PMID 40282303, 2025). "In addition to these cardiac-specific biomarkers, C-reactive protein (CRP) and lipoprotein-associated phospholipase A2 (Lp-PLA2) have emerged as significant markers in the broader context of cardiovascular diseases." (PMID 38251118, 2024). "CRP is elevated in cardiovascular diseases leading to inflammatory changes in the coronary vessels." (PMID 38433948, 2024). "In addition to its inflammatory effect, CRP is considered a prognostic marker in cerebrovascular and cardiovascular diseases." (PMID 39797144, 2024). "Investigating the potential of other inflammatory markers, such as TNF-α, MCP-1, and CRP, could provide a more comprehensive understanding of the inflammatory landscape in cardiovascular diseases." (PMID 39057626, 2024).
cardiovascular disease (continued). "In this study, endocan levels predicted cardiovascular disease much better than CRP." (PMID 39230149, 2024). "This is a very important finding because it is well known that in patients with known cardiovascular disease, elevated CRP results in substantially higher rates of recurrent vascular events despite reaching LDL-C goals, a phenomenon called residual inflammatory risk." (PMID 39795963, 2024). "CRP is an acute inflammatory protein and is mainly synthesized by interleukin-6 (IL-6)-dependent hepatic biosynthesis, and elevated CRP levels in the serum are an independent predictor of cardiovascular disease." (PMID 38233747, 2024). "However, several factors related to cardiovascular disease were improved, such as insulin sensitivity of adipose tissue, high sensitivity C-reactive protein (hs-CRP) and oxidized low-density lipoprotein cholesterol (LDL-C)." (PMID 38519764, 2024). "Our data indicate that persistent CRP−positivity and thus chronic low-grade inflammation in SSc patients enhance the risk for arteriosclerotic-cardiovascular disease significantly beyond the ASCVD risk observed for our SSc patients without CRP elevations." (PMID 39564499, 2024). "Increased levels of C-reactive protein (CRP), an indicator of systemic inflammation, have additionally been found in patients with PCOS, further contributing to an increased risk of the development of cardiovascular diseases." (PMID 38540265, 2024). "A recent study evaluating the use of salivary biomarkers to diagnose cardiovascular disease reported that some biomarkers, such as C-reactive protein, creatine kinase-myocardial band, myoglobin, and troponin I, showed significant promise in diagnosing the condition." (PMID 39685509, 2024). "Based on earlier cohort studies, cumulative exposure to risk factors such as blood pressure, blood lipids, C-reactive protein, UA, and the monocyte-to-HDL cholesterol ratio has been shown to have a greater impact on adverse outcomes such as cardiovascular disease than single measurements." (PMID 38155948, 2023). "Resting concentrations of CRP did not improve, regardless of individual pre-intervention cardiovascular disease (CVD) risk stratification." (PMID 37375567, 2023). "On the other hand, there is evidence in humans that supplementation of ALA in the diet is associated with an improved lipid profile, a reduction in the inflammatory biomarker C-reactive protein (CRP) and a reduction in cardiovascular diseases (CVDs) and all-cause mortality." (PMID 37047085, 2023). "High levels of CRP can be predictive markers for Met-S and cardiovascular disease." (PMID 37168278, 2023). "Our results also support the role of CRP as a marker of cardiovascular disease." (PMID 37623831, 2023). "Thus, further investigation is neededto determine how the two CRP isoforms contribute to atherogenesis and thedevelopment of cardiovascular disease." (PMID 39077585, 2023). "Furthermore, cardiovascular diseases exhibited a recurrence rate of 1.53% per person per year when CRP levels were below 2 mg/L, which then increased to 3.3% per person per year when CRP levels ranged from 8–10 mg/L." (PMID 37508329, 2023). "Similarly, patients demonstrated normalization of key biomarkers associated with cardiovascular disease including LDL-P (33.3%), LDL-C (13.4%), HDL-C (37.9%), CRP (33.2%), Apo-B (12.3%), Triglycerides (53.6%), and LP-PLA2 (43.2%)." (PMID 37942418, 2023). "Nevertheless, there is preliminary evidence suggesting a possible association between positive psychological processes (e.g., positive affect, gratitude) and lower levels of inflammatory markers (e.g., TNF-α, interleukin-6, C-reactive protein) in individuals with cardiovascular disease." (PMID 37213708, 2023). "The level of CRP in serum indicates the likelihood of a future cardiovascular disease." (PMID 38077410, 2023).
cardiovascular disease (continued). "In the general population without known cardiovascular disease, elevated CRP concentration is associated with an increased risk of vascular dysfunction." (PMID 37664733, 2023). "Furthermore, among subjects with IBD, those who developed cardiovascular diseases displayed higher levels of C-reactive protein (CRP)." (PMID 37260950, 2023). "Quantitative analysis of CRP levels in the blood can help in assessment and management of inflammatory periodontal disorders, as well as determination of the link between periodontal health and other issues such as cardiovascular disease." (PMID 37568846, 2023). "One of the RCTs that have addressed the anti-inflammatory properties of statins was the PRINCE (pravastatin inflammation/CRP evaluation) trial, which noted that statins were involved in the reduction of C-reactive protein (CRP) in patients suffering from cardiovascular diseases." (PMID 37242493, 2023). "CRP is a biomarker of cardiovascular diseases including vasculopathy and cardiomyopathy." (PMID 37484982, 2023). "Even if the precise form is yet unknown, CRP mediates tissue fibrosis in cardiovascular disease by activating TGF-β/Smad signaling through both TGF-β1-dependent and -independent mechanisms; it also upregulates PAI-1 expression and activity." (PMID 37873776, 2023). "For this reason, the fact that there is a relationship between IL-6 and cardiovascular disease in our work could be mediated by the interrelation between both IL-6 and CRP." (PMID 37762312, 2023). "Additionally, NLR correlated with the duration of cardiovascular disease, CRP, central diastolic blood pressure, and glomerular filtration rate." (PMID 37511843, 2023). "Additionally, it has been proven that statin administration decreases the plasma concentrations of CRP in patients with cardiovascular diseases." (PMID 36834166, 2023). "Recently, inhalation of fumes containing metal oxide nanoparticles by human volunteers was shown to increase blood levels of SAA and CRP before the onset of MFF symptoms, thus providing a link between inhalation of metal oxides and risk of cardiovascular disease." (PMID 36650530, 2023). "Importantly, it was stated that most autologous ligands recognized by CRP overlaps with those of antiphospholipid autoantibodies that are related to premature cardiovascular disease in autoimmune syndromes." (PMID 37873776, 2023). "Furthermore, evidence is accumulating that CRP has a direct role in the development or occurrence of cardiovascular diseases." (PMID 36894998, 2023). "A landmark study conducted in 109 patients receiving hemodialysis (HD) showed, for the first time, strong evidence that SAF is an independent risk factor for all-cause mortality in CKD, along with previous cardiovascular disease (CVD), serum albumin, and C-reactive protein (CRP)." (PMID 36978832, 2023). "Moreover, a meta-analysis about the effects of PTX on inflammatory markers in cardiovascular diseases showed that the anti-inflammatory effect of PTX was associated with a statistically significant reduction in the concentrations of TNF-α and CRP in plasma." (PMID 37107001, 2023). "C-reactive protein (CRP) levels in liver tissue and circulation also correlated highly (r = 0.73), which is of interest given the widespread use of this protein as a systemic risk marker for cardiovascular disease." (PMID 35654907, 2022). "A retrospective study of 539 testicular survivals showed that patients with CRP ≥ 1.5 mg/L had a larger risk of developing a non-germ cell second tumor and a higher risk of cardiovascular disease than survivors with CRP<1.5 mg/L." (PMID 35756636, 2022). "However, due to the reported elevated CRP levels in many clinical conditions, including various cardiovascular diseases, its potential use in the diagnosis and monitoring of PH patients remains limited." (PMID 35054082, 2022).